MIF (macrophage migration inhibitory factor)
Diseases named in the same sentence as MIF in open-access papers (continued):
Sharing a sentence is not in itself a finding about the gene and the disease.
tumor (continued). "Macrophage Migration Inhibitory Factor (MIF) and its homolog D-dopachrome Tautomerase (DDT) have been implicated as drivers of tumor progression across a variety of cancers." (PMID 39028303, 2024). "In order to further explore the specific receptors involved in the MIF pathway in FABP6+ tumor cells, we conducted an analysis and found a significant enrichment of CD74 and CD44 receptors in the tumor tissue." (PMID 38277205, 2024). "MIF attracts mast cells to the tumor environment and accumulation of MCs and their pSTAT5 expression correlates with the level of MIF." (PMID 38178143, 2024). "Tumor-mediated MIF signaling pathway also inhibits NK cell activity, aiding in the evasion of NB cells from NK cell-mediated cytolysis." (PMID 38948053, 2024). "The effects of radiotherapy and silence of MIF on tumor microvascular structure and HIF-α expression were also examined using the BM model of NSCLC described previously." (PMID 38685050, 2024). "It has been widely shown that MIF has a role in encouraging the invasion and metastasis of cancerous tumor cells." (PMID 38602556, 2024). "In vivo models treated with the small molecule antagonist CPSI-1306 exhibited reduced tumor apoptosis, tumor growth, and metastasis, suggesting MIF to be a potential treatment target in TNBC." (PMID 38732068, 2024). "MIF staining was intense in tumor cells, while CXCL12 and CD3 stainings were relatively weak and diffuse in paraffin sections of control samples." (PMID 38386050, 2024). "Chordal graphs illustrated the role of the MIF signalling pathway in cellular communication within tumour tissues, with the main targets being epithelial cells, CMP and Other_T cells." (PMID 39031800, 2024). "Our analysis identified the MIF pathway as the primary interaction between tumour and immune clusters." (PMID 39187937, 2024). "MIF-2) with close structural and functional similarities with MIF and an overlapping spectrum of activities such as tumor formation, growth and survival of cancer cells and tumor invasion." (PMID 38178143, 2024). "Since cancerous cells endogenously produce and release MIF, we wished to directly confirm that the source of the MIF that regulates immunosuppressive cell expansion, is secretion from the tumor cells." (PMID 39576827, 2024). ",107In vitro studies of human bladder tissue have supported a role of MIF in tumour cell proliferation." (PMID 38301482, 2024). "Given the high concentration of hepatic NK cells, tumor survival is conferred by MIF-mediated evasion of NK-driven cell lysis." (PMID 38732068, 2024). "The tumor microenvironment is complex, and in addition to calreticulin, abnormal expression of the regulatory protein macrophage inhibitory factor (MIF) can also have a great impact on the survival of tumor cells." (PMID 38464520, 2024). "We found that MIF/CXCR4 LR was the most common crosstalk between tumor cells and macrophages in G01 and G02." (PMID 39464891, 2024). "High expression of MIF had been observed to promote tumor progression and metastasis, stimulate angiogenesis, and create an immunosuppressive microenvironment conducive to tumor development." (PMID 39691708, 2024). "MIF drives tumor metabolic re-programming to confer survival in hypoxic environments by inducing anaerobic metabolism via the NF-κB and HIF-1α pathways." (PMID 38732068, 2024). "In the context of signal regulation by TEXs in tumor cells, our findings pointed to MIF-(CD74+CD44) as a significantly more potent regulatory signal, playing a pivotal role in driving malignant tumors." (PMID 38683136, 2024).
tumor (continued). "The current study demonstrated that the MIF - (CD74+CXCR4) ligand-receptor pair is significantly active in tumor cells with elevated IGF2BP1 expression." (PMID 39512352, 2024). "Subsequent study reported that MIF played a role in cell proliferation along with other tumour‐promoting processes." (PMID 38629624, 2024). "The CellChat results showed that the MIF/CXCR4 axis was the main crosstalk type between tumor cells and macrophages." (PMID 39464891, 2024). "Metabolic pathway analysis reflected the adaptability of macrophages and CAFs to the tumor microenvironment, and the MIF signaling pathway was identified as a key mediator of cellular interactions." (PMID 39044973, 2024). "Combined DDT and MIF knockdown exhibited the largest reduction in tumor growth and angiogenesis, further highlighting their synergistic roles and the potential for dual blockade in antitumor treatment." (PMID 38732068, 2024). "Studies have demonstrated that inhibition of MIF expression in tumor cells leads to down-regulation of OPA1 and MFN1 while up-regulating DRP1 expression, resulting in mitochondrial fragmentation." (PMID 38405130, 2024). "Macrophage migration inhibitory factor (MIF), a crucial component of tumor exosomes, emerges as a vital molecule in the induction of MDSCs." (PMID 38756774, 2024). "We further explored how microglia regulated by the MIF/CD74 signaling axis exerts tumor-regulating effects." (PMID 38685050, 2024). "Communication target analysis revealed a significant enrichment of the MIF signaling pathway, and our results suggested that tumor cells acted as senders of the MIF signaling pathway, while CD8T cells acted as receivers of the signals." (PMID 38625586, 2024). "Detailed analysis of macrophage-related signaling pathways revealed an increase in the activity of SPP1 and MIF pathways in tumors, potentially related to macrophages promoting tumor growth, invasion, or immune suppression (left)." (PMID 39850883, 2024). "On the other hand, extracellular MIF is necessary for steady-state activation of Rho GTPase members, resulting in tumor invasion and metastasis." (PMID 38297333, 2024). "The upregulation of MIF is documented to attenuate E-Cadherin in tumor cells, consequently augmenting their proliferation, invasive properties, and migratory capacity in vitro." (PMID 38683136, 2024). "The MIF pathway is essential in orchestrating the immune responses within the tumor milieu, especially in modulating cellular interactions and immune cell activity." (PMID 38596689, 2024). "MIF induces HMGB1 secretion from tumor cells, which subsequently binds TLR4 and activates NF-κB-mediated cell migration." (PMID 38732068, 2024). "Tumor cell-derived MIF promotes expansion of Tregs (consistent with the IL-2 ARP we observed in CD4+ T cells via ASPEN) and inhibits CD8+ T cell activation." (PMID 39483921, 2024). "The MIF is regarded as a proinflammatory cytokine and contributes in the progress of oncogenesis by endorsing tumor development, altering immunological responses, enhancing inflammation, and aiding cancer-associated angiogenesis." (PMID 38916819, 2024). "With regard to the action of inflammatory mediators in endorsing oncogenesis and tumor progression, evidence is pointing towards a probable correlation amongst macrophage migration inhibitory factor (MIF) expression and tumorigenesis and cancer progression." (PMID 38916819, 2024). "Macrophage migration inhibitory factor (MIF) is an immune cytokine with pro-inflammatory, enzymatic, and hormonal functions implicated the pathogenesis of inflammatory and neoplastic diseases." (PMID 38476376, 2024). "Levels of MIF are elevated in NB tumor tissues and cell lines, contributing to the increased aggressiveness of NB and assisting in immune evasion." (PMID 38601081, 2024). "Simultaneously, exhausted T cells and CAFs antagonized the anti-tumor functions of aDCs via the MIF | CD74 receptor-ligand." (PMID 38565865, 2024).
tumor (continued). "In xenograft murine models, administration of the MIF/DDT antagonist 4-IPP led to reductions in tumor burden and metastases." (PMID 38732068, 2024). "Cellular communication analysis identified increased interactions between FABP6+ tumor cells and T cells, with the involvement of the MIF-related pathway and the CD74-CD44 interaction." (PMID 38277205, 2024). "The protumoral effects exerted by MIF were further supported in vivo, where MIF deficiency, or its inhibition with 4-iodo-6-phenylpyrimidine (4-IPP), causes tumor-associated MΦ to revert towards an M1-like, inflammatory phenotype." (PMID 38548753, 2024). "In conclusion, our newly developed allosteric MIF tautomerase inhibitor MN123 and MIF‐PROTACs can enhance ferroptotic cell death and persistently inhibit tumor cell proliferation in combination with a non‐toxic dose of GPX4 inhibitor RSL3." (PMID 38924362, 2024). "There is substantial scientific evidence that cancer cells utilize secreted MIF to evade immune cell–mediated antitumor responses in the tumor microenvironment." (PMID 37067909, 2023). "These cells help tumor metastasis by producing exosomes that contain a large amount of macrophage migration inhibitory factor (MIF)." (PMID 37287924, 2023). "Macrophage migration inhibitory factor (MIF) is an inflammatory molecule that is involved in a variety of neoplastic diseases." (PMID 35138531, 2023). "Strikingly, MIF communication was significantly more potent in the HCC environment than in the non-tumor environment." (PMID 37842089, 2023). "The pro-oncogenic role of MIF has been reported for certain types of cancers, such as glioblastoma, melanoma, gastric cancer, and NB, enhancing tumor growth, invasiveness, and angiogenesis." (PMID 37611092, 2023). "Ligand MIF, a protumor and antitumor mediator depending on tumor context, exhibited a stronger interaction with receptors on stromal cells in the high UVRAG expression group." (PMID 37173968, 2023). "Emerging soluble factors that have gained attention over the past years as contributors to tumor progression are the members of the macrophage migration inhibitory factor (MIF) family of proteins." (PMID 36672343, 2023). "Another team found that blocking PaC tumor cell release of EVs containing macrophage migration inhibitory factor (MIF) can prevent liver metastasis formation." (PMID 37345116, 2023). "The high levels of MIF present in tumors, in addition to providing an advantage in terms of tumor growth, also grant the cancer cells a particular aggressiveness, making them more prone to migrate and metastasize." (PMID 36672343, 2023). "Our study highlights that tumor-associated fibroblasts (especially FAP + and MFAP5 + fibroblasts) can secrete MIF, which binds to the corresponding receptor CD74 on macrophages to drive immunological escape." (PMID 37344903, 2023). "Several factors secreted by tumor cells, such as granulocyte-colony stimulating factor (G-CSF), macrophage migration inhibitory factor (MIF), TNF-α, and autophagosomes (TRAPs), have been shown to upregulate PD-L1 expression on macrophages." (PMID 37313405, 2023). "The expression of MIF had positive correlation with angiogenic growth factor expression, microvascular density, and tumor-related new blood vessel formation." (PMID 37213285, 2023). "The results of our study indicate that tumor cells with high m7G scores exhibit stronger communication with LAMs through MIF and TGF-β signaling communication." (PMID 37868988, 2023). "Within the tumor microenvironment, increases in intratumorally activated DCs and IFN-γ-producing CD4+ and CD8+ T cells were found in the group inoculated with the MIF-deficient cancer cells." (PMID 36672343, 2023). "The reduction of MIF in TAMs resulted in a significant reduction of factors that marks M2 polarization, meanwhile, the reduction of MIF in tumor cells resulted in a significant decrease of tumor cell proliferation and an increase of tumor cell apoptosis." (PMID 36794651, 2023).
tumor (continued). "MIF is a pleiotropic cytokine overexpressed in many tumors and has pro-inflammatory and tumor-promoting activities." (PMID 37842089, 2023). "As examples, MIF-(CD74 + CXCR4) interaction was decreased between tumor and most immune cell types post-treatment." (PMID 36417130, 2023). "Studies have shown that MIF can affect the migration of tumor cells and inhibit immune cell infiltration into tumor tissue, affecting tumor cells and tumor stroma through multiple mechanisms." (PMID 37842089, 2023). "NKG2D is transcriptionally downregulated by MIF in NK cells, which reduces their capacity to eradicate tumor cells." (PMID 37298230, 2023). "MIF also plays a multifaceted role promoting tumor progression, metastasis and angiogenesis, in the context of cancer." (PMID 37981907, 2023). "There is evidence that MIF acts as a chemokine that facilitates the recruitment of immune cells to the tumor site." (PMID 36768437, 2023). "In the analysis of pathways based on L/R pairs between tumor cells and PCs, midkine (MK) and macrophage migration inhibitory factor (MIF) signaling were the most significantly enriched pathways." (PMID 37138324, 2023). "Interactions of tumor cells with the BM microenvironment involve preferred communication with myeloid cells through the MIF/CD44/CD74/CXCR4 and MK/LRP1/NCL axes." (PMID 37365178, 2023). "Considering all this information, it is clear that MIF promotes tumor establishment and impairs the ability of the immune system to fight back." (PMID 36672343, 2023). "Significantly, β-catenin-dependent modulation has also been described to be impacted by MIF, essentially by inducing tumour expression of cyclooxygenase-2 (COX-2), which reduces intratumor trafficking of CD103+ DCs." (PMID 37454231, 2023). "Chemokine-like function of MIF consists of the recruitment of immune cells and mediation of acute and chronic inflammatory diseases, and tumor progression and development." (PMID 37869102, 2023). "There is broad consensus that MIF and D-DT often share similar roles to promote malignant transformation, tumor growth, and metastasis." (PMID 37464010, 2023). "TNF-related interactions such as TNF_VSIR and CD74_MIF interactions are enriched in SN, exhibiting more inflammation-related tumor features." (PMID 37745301, 2023). "Collectively, our findings provide a comprehensive HCC transcriptomic landscape at the single-cell level and identify novel mechanisms by which CD36+ CAF-secreted MIF induced by lipid peroxidation regulates the immune evasion of tumor cells." (PMID 36878933, 2023). "Other reviews have also indicated that inflammatory cytokines, such as interleukin(IL)-1, IL-6, IL-10, tumor necrosis factor-α, macrophage migration inhibitory factor, and transforming growth factor-β, are involved in tumor initiation and progression." (PMID 36855430, 2023). "MIF upregulation forms a pro-tumor microenvironment in response to hypoxia-induced factors and promotes pro-inflammatory cytokine production." (PMID 37240298, 2023). "MIF is secreted by exhausted T cells in the tumor which supports the polarization of macrophages to immunosuppressive phenotypes." (PMID 37067909, 2023). "Suggesting that more intense levels of oxidative stress in the tumor microenvironment induced MIF secretion to promote HCC cell survival and immunosuppression." (PMID 37842089, 2023). "Its redox-dependent conformational isoform, termed oxidized MIF (oxMIF), is a promising tumor target due to its selective occurrence in tumor lesions and at inflammatory sites." (PMID 37067909, 2023). "The inferred MIF signaling network further revealed that tumor cells and CAFs are prominent sources of MIF ligands acting on MDSCs (CD33+CD11b+HLA-DRlo), monocytes or macrophages and DCs." (PMID 36878933, 2023). "MIF OE has been reported in diverse cancers including NB, where it has been shown to enhance tumor growth, invasiveness, and angiogenesis." (PMID 37611092, 2023).
tumor (continued). "Here, we determined that patients with the MIF SNP rs755622 have an altered tumor microenvironment characterized by increased lymphocyte infiltration and enhanced lactotransferrin (LTF) expression." (PMID 37252795, 2023). "We observed that several pro-tumor signal pathways were primarily present between these cells, including MIF, FN1, TGF-β and COLLAGEN pathways." (PMID 37344903, 2023). "MIF also has been described to be a pro-tumorigenic factor in various cancers that promotes angiogenesis, increases cell proliferation, and modulates tumor immunity." (PMID 37464010, 2023). "In the MIF signaling pathway, tumor cells were the main output cells, especially interferon-like tumor cells (which were also the main signaling cells in all pathways), whereas PCs were the main receiver cells." (PMID 37138324, 2023). "Within the TME, the tumor homing of mesenchymal stromal cells is regulated by the MIF-(CD74 + CXCR4) ligand–receptor pair in the MIF pathway." (PMID 37874419, 2023). "The study found that astrocytes were activated by tumor cell-oriented factors, including macrophage migration inhibitory factor (MIF), IL-8, and plasminogen activator inhibitor-1 (PAI-1)." (PMID 37190188, 2023). "The obtained results revealed significantly elevated levels of TNF-α and TGF-β coupled with higher expression of the MIF mRNA in the DMBA group as compared to the control group confirming the tumor aggressiveness." (PMID 35138531, 2023). "In vivo evaluation of DCA treatment on tumor growth and MIF gene expression was performed in the xenograft model." (PMID 37359381, 2023). "Each cell cluster exhibited significant MIF pathway communication in incoming and outgoing modes under non-tumor and HCC conditions." (PMID 37842089, 2023). "The presence of MIF was associated with increased recruitment of CD8+ T cells to the tumor site, thus establishing a regulatory role for MIF in T-cell trafficking." (PMID 36768437, 2023). "MIF increases malignant transformation, tumor growth, and metastatic potential, moreover, in many tumor cells and pretumor states elevated MIF and mRNA levels have been observed." (PMID 37485818, 2023). "Macrophage migration inhibitory factor (MIF) is a well-characterized immunosuppressive factor that is secreted by immune cells and plays an important role in tumour immune escape by binding to its receptor CD74." (PMID 37491279, 2023). "The role of MIF and its receptors in the tumour microenvironment has been reported in other tumours." (PMID 35060345, 2022). "Macrophage migration inhibitory factor (MIF) is a pro-inflammatory factor overexpressed in several solid tumors to accelerate tumor development and metastasis." (PMID 35963853, 2022). "In this review, the tumor-promoting effects and related mechanisms of TA-MSCs, TA-MSCs-EVs and MIF as well as their potential interrelationships are comprehensively summarized." (PMID 35842634, 2022). "For example, tumor-derived exosomes containing increased levels of macrophage migration inhibitory factor (MIF) were shown to educate KCs and promoted TGF-β production." (PMID 36436127, 2022). "Accordingly, TA-MSCs and tumor cells form a positive feedback loop of intercellular interactions through MIF that continuously promotes malignant progression." (PMID 35842634, 2022). "MIF signaling has been previously related to drug resistance in different tumor types, including NB and other developmental tumors." (PMID 35715791, 2022). "Although recent studies have indicated that MIF is involved in the regulation of autophagy in tumor cells, its role is unclear." (PMID 35280512, 2022). "In mononuclear macrophages, tumor-derived MIF can initiate monocyte-dependent angiogenesis, suggesting an important functional role of MIF in the polarization of M2 macrophages." (PMID 36551288, 2022). "Cytokine profiling and RNA-sequencing data analysis revealed NB cells as the main source of MIF in the BM, suggesting a potential role of MIF in tumor invasion." (PMID 35715791, 2022).